DBF4P1 (DBF4 pseudogene 1)
Gene: Processed pseudogene on chromosome 10 (64,168,959 to 64,170,850, reverse strand). Ensembl gene ENSG00000235489.
Diseases named in the same sentence as DBF4P1 in open-access papers:
DBF4P1 is named in the same sentence as 1 disease in open-access papers, as found by Europe PMC text mining. Sharing a sentence is not in itself a finding about the gene and the disease.
DBF4P1 shares sentences with these, for which no sentence is quoted: cancer (1 paper).